CRP (C-reactive protein)
Diseases named in the same sentence as CRP in open-access papers (continued):
Sharing a sentence is not in itself a finding about the gene and the disease.
Obesity (continued). "Accordingly, in our cohort, cRAGE inversely correlates with the inflammatory marker PAI-1, known to increase in age-associated clinical conditions including cardiovascular diseases, type 2 diabetes (T2DM), obesity and inflammation and shows also an almost significant inverse correlation with CRP." (PMID 30903794, 2019). "Notably, individuals with obesity exhibited increased (p < 0.01) circulating concentrations of the inflammatory markers CRP, fibrinogen and uric acid." (PMID 30970605, 2019). "The association between SRH and progression to metabolically unhealthy status was much stronger in individuals with obesity than those without, especially in relation to any metabolic abnormality, fatty liver, and high C-reactive protein (all p for interaction by obesity <0.05)." (PMID 30609650, 2019). "Age ≥ 60 years (HR = 2.32, 95% CI: 1.87–6.15), obesity (HR = 1.84, 95% CI: 1.35–2.49), hs-CRP (HR = 1.39, 95% CI: 1.16–2.68), a high adiponectin level (HR = 2.76, 95% CI: 1.08–4.61), and multi-vessel lesions (HR = 2.67, 95% CI: 1.13–6.21) were associated with MACEs." (PMID 30979830, 2019). "This population-based, retrospective cohort study included all residents of Alberta, Canada, aged 18 years and older with at least 1 procedure to ascertain severe obesity and measures of C-reactive protein, fasting glucose, triglyceride, and high-density lipoprotein cholesterol levels." (PMID 31469399, 2019). "The increase in obesity showed a direct effect on IL-6 (males 0.36, 95% CI 0.28, 0.43; females 0.58, 95% CI 0.51, 0.64) and CRP (males 0.76, 95% CI 0.62, 0.90; females 1.00, 95% CI 0.86, 1.13) and an inverse relationship with adiponectin in females (-2.43 95% CI -4.37, -0.50)." (PMID 31071114, 2019). "C-reactive protein is also chronically elevated in low-grade inflammatory conditions like obesity." (PMID 31151202, 2019). "The absolute increase in CRP with obesity is higher than when the individual is overweight." (PMID 30692559, 2019). "Overall, the contribution of WHR and CRP to the metabolic profile shows that beyond increased whole-body fat mass (measured by BMI and leptin), visceral adipose tissue and related systemic inflammation play a role in obesity-related GMV reductions." (PMID 31427957, 2019). "Data from animal and human studies have shown that obesity leads to a systemic proinflammatory state as indicated by higher plasma concentrations of various inflammatory markers, including CRP, interleukin 6 (IL-6), tumor necrosis factor α (TNF-α), and monocyte chemoattractant protein 1 (MCP-1)." (PMID 31192262, 2019). "Obesity leads to a pro-inflammatorystate with increased CRP, which may interfere with the interpretation ofthis laboratory test in AA." (PMID 29513800, 2018). "CRP, on the other hand, is known as a marker of inflammation that is strongly related to obesity." (PMID 30383538, 2018). "Recent studies have confirmed that obesity is a state of low-grade chronic inflammation that is characterised by increased concentrations of C-reactive protein (CRP), tumour necrosis factor-alpha (TNF-α), interleukin-6 (IL-6), and other inflammatory markers in the blood." (PMID 30914847, 2018). "Obesity is characterized by low-grade systemic inflammation with increased levels of C-reactive protein (CRP), proinflammatory cytokines and adipose-derived cytokines, including leptin and adiponectin which may play a role in iron homeostasis." (PMID 30275363, 2018). "CRP values increased according to patients’ BMI, with varying sensitivityfrom 79.78% in subjects with normal or lean BMI, 87.87% in overweight, and93.5% in individuals with obesity." (PMID 29513800, 2018). "Furthermore, obesity was associated with elevated plasma TAG, cholesterol, CRP and serum insulin concentrations, and increased HOMA‐IR (P < 0.05)." (PMID 30009507, 2018).
Obesity (continued). "The current study contradicts this evidence, since we did not report any association between MetS, or body shape, on CRP levels, even though clear differences were observed for other body compositional measures of obesity." (PMID 29618342, 2018). "The meta-analysis results regarding metabolic and obesity markers indicated that triglycerides, total cholesterol, CRP, BMI, total body fat percentage, waist circumference, waist–hip ratio, systolic BP, and leptin levels were positively correlated with chemerin levels." (PMID 29720894, 2018). "Obesity, high baseline CRP and male sex predicted progression of ≥ 2 mSASSS units over 5 years." (PMID 30075808, 2018). "Indeed, obesity induces a chronic, low-grade inflammation with overexpression of C-reactive protein and hepcidin that is negatively correlated with both maternal and cord blood iron status." (PMID 30186542, 2018). "Therefore, high CRP values in subjects with obesity should be lessappreciated than in a normal BMI subject, due to the risk to incur in a falsepositive case." (PMID 29513800, 2018). "In fact, prevalence of increased C-reactive protein (CRP) levels, a marker of inflammation, in HD patients was higher in Western countries than in Japan and of catheter use for HD and obesity, which can increase inflammation, was lower in HD patients of Japan than those of Western countries." (PMID 29596361, 2018). "Moreover, as other authors have also reported for CVD, CRP levels can be confounded by obesity, ethnicity, gender, and other comorbidities." (PMID 30154790, 2018). "Increased CRP and haptoglobin levels are indicators of inflammation observed in human obesity." (PMID 30005082, 2018). "In addition, a cross-sectional study of an Israeli population found that subjects with obesity had markedly higher CRP levels than normal-weight persons." (PMID 30294302, 2018). "Obesity is a metabolic disease characterized by low grade chronic inflammation, usually accompanied by dyslipidemia and up-regulation of other bioactive molecules such as CRP and TNF-α." (PMID 30572569, 2018). "Markers of inflammation, such as tumor necrosis factor alpha (TNF-α), interleukin-6 (IL-6), CRP and MCP-1, are increased in peripheral blood levels in obesity and are associated with IR and may predict the development of type 2 diabetes." (PMID 29694633, 2018). "Consistent with this hypothesis, Miller and colleagues (2002) noted a synergistic relationship between depression and obesity with respect to CRP levels." (PMID 30524737, 2018). "Those with unreported sleep disturbance had significantly higher odds of elevated CRP levels (>1 mg/L) than those without sleep disturbances (OR 1.34), although the association was not significant when adjusted for obesity and other controls." (PMID 30402295, 2018). "Thus, the purpose of this research is to examine the independent and combined effects of loneliness and obesity on elevated CRP in older adults." (PMID 30439985, 2018). "Furthermore, a strong link exists between obesity and altered glucose metabolism, and pro-inflammatory markers such as C-reactive protein (CRP), interleukin-6 (IL-6) and tumour necrosis factor alpha (TNF-α)." (PMID 28193219, 2017). "In conclusion, strong and consistent patterns of association between elevated CRP or AGP and covariates were limited to positive associations with recent fever and malaria (CRP and AGP), recent diarrhea, stunting, and elevated AGP in PSC and with overweight and obesity and elevated CRP in WRA." (PMID 28615263, 2017). "Inflammation and obesity have a complex interplay, which a bidirectional MR study clarified as adiposity likely causing higher CRP rather than CRP causing adiposity." (PMID 28819125, 2017). "COH women present abnormalities in non-standard markers of cardiometabolic risk (sRAGE, leptin, high sensitive C-reactive protein), supporting the view that there is no healthy pattern of obesity." (PMID 28409494, 2017).
Obesity (continued). "Therefore, low levels of vitamin D are negatively associated with markers of inflammatory activation (C-reactive protein, CRP) and obesity." (PMID 28176237, 2017). "In our study, the 16 weeks of fructose loading in rats resulted in obesity, hyperglycemia, hypertriglyceridemia, systemic oxidative stress, and an almost twofold increase in UA and CRP levels, which is probably closely related to the morphological changes in the kidneys." (PMID 29321950, 2017). "Circulating levels of CRP could be influenced by age, degree of obesity, sex, smoking status, and use of medications." (PMID 28801571, 2017). "We also evaluated COC use, obesity or both in relation to cardiovascular risk factors categorized according to the American Heart Association, considering HDL-c ≤ 50 mg/dL, CRP ≥ 3 mg/L, fibrinogen ≥ 350 mg/dL, SBP ≥ 140 mmHg, DBP ≥ 90 mmHg, and total cholesterol ≥ 240 mg/dL." (PMID 29033897, 2017). "HRs and 95% CIs were calculated using Cox proportional hazards models, adjusted for confounding factors; in another model, they were additionally adjusted for potential mediators, including obesity, C-reactive protein, glucose and insulin, as well as for levels of total oestradiol and androgens." (PMID 28721436, 2017). "When stratified according to nutritional status, we found progressively impaired values for fasting insulin, HOMA-IR and HOMA-β with increasing severity of obesity, while CRP presented a significant difference only at obesity level I and total cholesterol at obesity level III." (PMID 29116305, 2017). "Obesity is a major determinant of elevated CRP in multiple populations." (PMID 28687081, 2017). "In a pooled analysis of the 2 malarial countries that measured anthropometric measures (Cameroon, Cote d’Ivoire), obesity and malaria were significantly associated with both elevated CRP and AGP (data not shown)." (PMID 28615263, 2017). "The finding of higher levels of plasma CRP, TNF-a and IL-6 in the obese is also consistent with the findings of others suggesting the presence of chronic, systemic inflammation associated with obesity." (PMID 27513854, 2016). "Increased levels of CRP were found due to obesity (P<0.001) and also the presence of CC (P<0.001)." (PMID 27612200, 2016). "Recently, the obesity has been considered a physiological state of chronic inflammation, characterized by elevated levels of inflammatory markers including C-reactive protein (CRP), interleukin-6 (IL-6), and tumor necrosis factor alpha (TNF-α)." (PMID 27899895, 2016). "Guven and colleagues also found that OSA was associated with elevated CRP levels independent of obesity." (PMID 27684378, 2016). "In addition, plasma PLP concentration has been inversely associated with circulating concentration of C-reactive protein (CRP), a marker of systemic inflammation that is elevated in obesity." (PMID 27598193, 2016). "The connection between high levels of CRP and obesity is well known." (PMID 28007936, 2016). "Obesity causes a low-grade inflammation and is associated with a chronic inflammatory response and increased levels of tumor necrosis factor-α (TNF-α), interleukin-6 (IL-6) and/or C-reactive protein (CRP)." (PMID 27136447, 2016). "However, not all studies in adults or in children have confirmed the putative association between CRP levels and OSA severity, owing to small sample sizes and inadequate consideration of confounding factors such as obesity." (PMID 27684378, 2016). "Although all participants had body mass index ≤ 35 kg/m2, some participants had body mass index > 30 kg/m2, and CRP level may increase with obesity." (PMID 25595197, 2015). "Our findings are consistent with the results of other studies showing an inverse association of serum 25(OH)D concentrations with health events or biomarkers we had included in our AL index, including obesity, hypertension, insulin resistance, CRP concentrations, and dyslipidemia." (PMID 26451600, 2015).
Obesity (continued). "A link between obesity and inflammation has been initially hypothesized based on the observation of increased levels of IL-6 and C-reactive protein (CRP) in obese animals and humans." (PMID 26089771, 2015). "A strong relationship between obesity and CRP has been observed in all populations." (PMID 26870128, 2015). "Liver and adipose tissue produce CRP and both may contribute to elevated plasma CRP levels in obesity." (PMID 26380303, 2015). "A few association studies have also identified the connection between hs-CRP and obesity." (PMID 26177029, 2015). "Because the correlations between LEP DNA methylation levels and BMI were attenuated after adjusting for CRP levels, we hypothesized that the obesity-related proinflammatory response per se contributed to the alteration of LEP epigenetic profile in blood cells." (PMID 25929254, 2015). "On the other hand, obesity could trigger insulin resistance in some cases via increased C-reactive protein (CRP) levels in late pregnancy, when it may relate to pregravid BMI and not to gestational diabetes mellitus." (PMID 26475596, 2015). "Children with overweight and obesity have higher concentrations of serum CRP, which supports the hypothesis of a relationship between childhood obesity and the presence of systemic inflammatory substances." (PMID 25874126, 2015). "In addition, a recent report showed an inverse correlation between β-cryptoxanthin serum concentration and obesity, which was directly related to CRP in the general population instead." (PMID 26437420, 2015). "The meta-analyses of MS and obesity markers indicated that TG, TC, CRP BMI, TBF%, WC, WHR and Leptin were positively correlated with chemerin, nevertheless, SBP, DBP, LDL-C, HDL-C, ALT and r-GT were not significantly correlated, adiponectin was negatively correlated." (PMID 25469985, 2014). "In obesity, CRP has also been postulated to be involved in the development of leptin resistance." (PMID 24944619, 2014). "The pathophysiological mechanisms linking obesity to elevated levels of CRP are well recognized." (PMID 25276234, 2014). "Furthermore, there is always a limitation in analyzing multiple factors in biological systems (e.g. leptin, CRP and obesity) due to the adjustments that have to be made for common disease pathways." (PMID 24944619, 2014). "While the association between leptin and CRP was independent of obesity level, there was a statistically significant increase in the concentration of these markers as the level of obesity increased." (PMID 24944619, 2014). "Neighborhood deprivation was significantly and positively associated with obesity, high waist circumference, high blood pressure, high fasting blood glucose, high triglycerides, low-HDL, the metabolic syndrome, and C-reactive protein (all significance levels p < .01)." (PMID 25539758, 2014). "We found 2 remarkably well conducted RCTs without benefits in low inflammatory conditions (old age and obesity) that met most of our proposed criteria (initial 25(OH)D<50 nmol/L, final 25(OH)D >75 nmol/L; baseline CRP elevated, and physiological doses of vitamin D3 used)." (PMID 26413186, 2014). "Recently, it has been demonstrated that obesity is associated with a low-grade inflammatory process, characterized by increased circulating levels of proinflammatory cytokines such as TNF-α, IL-6, and acute-phase proteins (CRP)." (PMID 24741576, 2014). "Second, individuals with obesity have more intense systemic inflammation with elevated levels of C-reactive protein and pro-inflammatory cytokines, both of which could promote the development of cataract." (PMID 24587127, 2014). "Similarly, in a cohort of 454 untreated OSAS patients, OSAS severity was an independent predictor of CRP levels but interacted with obesity and thus was found only in obese patients." (PMID 25538852, 2014).
Obesity (continued). "Accumulating evidence suggests that obesity—in particular central/visceral accumulation of fat—and its co-morbidities correlate with increases in circulating levels of inflammatory proteins such as C-reactive protein and IL-6." (PMID 24447654, 2014). "Moreover, CRP has been shown to be expressed in adipocytes in response to proinflammatory mediators, representing yet another link between obesity and chronic inflammation." (PMID 27433484, 2014). "A negative association of reduced ZAG and increased CRP or MCP-1 was also reported in obesity, insulin resistance, and metabolic syndrome." (PMID 24899788, 2014). "And CRP was noted as a marker of obesity related inflammation." (PMID 25198106, 2014). "Interactions were observed for several genotypes with obesity in determining CRP." (PMID 25393688, 2014). "In addition, the association between CRP and obesity is higher in women in many North American and European studies, and the obesity has been shown to be the most important predictor of CRP." (PMID 25309988, 2014). "In this study, the NAFLD was associated with hs-CRP in apparently healthy Asian Indians independent of obesity and abdominal obesity." (PMID 23326306, 2013). "Descriptive statistics of all study participant serum samples tested for Bone Panel (osteoprotegrin (OPG), leptin, parathyroid hormone (PTH) and insulin), Matrix Metalloproteinase Panel (MMP-2, MMP-8, MMP-9) and Obesity Panel (adiponectin and C-reactive protein (CRP))." (PMID 23577067, 2013). "This hypothesis is in agreement with previous data from our group showing that visceral fat contributes to increased plasma IL-6 and CRP in obesity." (PMID 23984354, 2013). "Whether this finding supports past studies that suggest the probable involvement of CRP with metabolic syndrome and obesity still requires further study." (PMID 23826157, 2013). "It has been reported that CRP is more closely correlated with obesity than metabolic syndrome." (PMID 24069195, 2013). "The correlations of leptin with CRP and white blood cells, which were found also in the present study, confirm the implication of this peptide in sustaining the low-grade inflammation and, ultimately, β-cell dysfunction in obesity." (PMID 24454366, 2013). "The concentration levels of fibrinogen and CRP were significantly higher among those in very high obesity risk category compared to those in no risk category." (PMID 23844088, 2013). "IL-6 by itself further increases the production of CRP in obesity." (PMID 23617205, 2013). "On the contrary, these levels are not influenced by global obesity, MetS, CRP, HOMA-IR, ALT or by genomic variants related to PNPLA3, chronic inflammation, and oxidative stress in the overall population." (PMID 23935829, 2013). "Diet-induced obesity-associated inflammation is characterized by an increased abundance of M1 macrophages in the adipose tissue, which are postulated to be major sources of several molecular mediators, such as TNF, IL-6, and C-reactive protein." (PMID 23922979, 2013). "Descriptive statistics of all study participant saliva samples tested for Bone Panel (osteoprotegrin (OPG), leptin, parathyroid hormone (PTH) and insulin), Matrix Metalloproteinase Panel (MMP-2, MMP-8, MMP-9) and Obesity Panel (adiponectin and C-reactive protein (CRP))." (PMID 23577067, 2013). "Our result showed that elevated CRP level was associated with lowered HDL and overweight/obesity." (PMID 24170724, 2013). "Plasma levels of CRP were strongly correlated with all important measures, cIMT, distensibility, BMI/waist:hip and as well as SBP, demonstrating a crucial role of inflammation in the development of obesity and obesity associated CVD." (PMID 23342053, 2013). "Although confounded by factors such as age, diabetic status, hypertension, and obesity, indicators of chronic inflammation (C-reactive protein, fibrinogen, white-cell count, and platelet activating factor acetyl hydrolase) significantly associate with increased risk of CAD." (PMID 24015188, 2013).